ENSG00000221060
Synonyms: LOC124900353
Gene: Small nucleolar RNA gene on chromosome 14 (69,804,203 to 69,804,331, reverse strand). Ensembl gene ENSG00000221060.
Gene Ontology:
Biological process: RNA processing
Cellular component: nucleolus
Homologues: Paralogues in human: SNORA11D (78% identical), SNORA11E (78% identical), SNORA11B (76% identical), SNORA11F (76% identical), SNORA11C (74% identical), SNORA11 (73% identical), SNORA11G (64% identical).